GLS (glutaminase)
Diseases named in the same sentence as GLS in open-access papers (continued):
Sharing a sentence is not in itself a finding about the gene and the disease.
cancer (continued). "Given that xCT/SLC7A11 expression correlates with the ability of cystine to induce glutamine anaplerosis, we reasoned that xCT/SLC7A11 expression might also be a determinant of glutaminase dependence in cancer cells." (PMID 28826492, 2017). "Indeed, expression of glutaminase (GLS) isozymes, the enzymes that catalyze deamination of glutamine to glutamate, correlates with growth rate and malignancy of certain cancer cells." (PMID 28553292, 2017). "Moreover, allosteric sites of metabolic enzymes, such as pyruvate kinase, isocitrate dehydrogenase (IDH), and glutaminase, have been proposed as important targets for specific cancer therapies." (PMID 27756303, 2016). "Therefore, several research groups are currently studying the possibility of developing a glutaminase inhibitor as an anti-cancer drug." (PMID 27440433, 2016). "We also address the GLS inhibitors and their utilization in the cancer therapy." (PMID 26402672, 2015). "Many glutamine transporters and GLS are upregulated in cancer." (PMID 26425657, 2015). "Bacterial L-asparaginases have been used as anti-cancer drugs for over 4 decades though presenting, along with their therapeutic efficacy, several side effects due to their bacterial origin and, seemingly, to their secondary glutaminase activity." (PMID 25664771, 2015). "In addition, it has been suggested that increased glutaminase expression in cancer cells can counterbalance decreased glutamate levels, especially in a glutamine-rich environment." (PMID 26499495, 2015). "Specific inhibitors of GLS have been shown to induce cell death in cancer cells." (PMID 26402672, 2015). "The inhibition of glucose utilization is accompanied by a down-regulatory effect of STS on the glutamine transporters Slc1a5 and glutaminase, which catalyze glutamine catabolism and provide cancer cells with bio-synthetic precursors for aminoacids and DNA synthesis." (PMID 25909219, 2015). "Glutaminase, which converts glutamine to glutamate, is involved in Warburg effect in cancer cells." (PMID 25026281, 2014). "The glutamine catabolism could be stimulated by oncogenic transcription factor c-MYC to fuel proliferation of cancer cells through up-regulating glutaminase (GLS)." (PMID 25153931, 2014). "As a result, targeting glutaminase as a cancer therapeutic has garnered significant attention." (PMID 25502225, 2014). "However, only a few series of glutaminase inhibitors for GLS1 have been identified, and only partial in vivo anti-cancer efficacy has been demonstrated." (PMID 25026281, 2014). "Because glutaminase inhibition in cancer cells decreases cellular energy production and results in nutrient depletion; and because autophagy is generally activated by conditions of nutrient deprivation, we concluded that induction of autophagy by AV-1 treatment was responsible for cell death." (PMID 25026281, 2014). "Furthermore, inhibition of glutaminase activity by the active alkyl benzoquinone AV-1 in carcinoma cells led to autophagy via AMPK-mediated ULK1 activation and mTORC1 inhibition, ultimately leading to inhibition of cancer cell growth." (PMID 25026281, 2014). "Therefore, the alkyl benzoquinones inhibited carcinoma cell growth by inhibiting cellular glutaminase activity." (PMID 25026281, 2014). "Glutaminase C is known as an important protein in cancer related research." (PMID 24098668, 2013). "An important goal of our future studies will be to identify the post-translational modification site(s) that leads to the activation of glutaminase in transformed/cancer cells, as this will hopefully provide clues toward understanding the mechanism by which NFκB regulates enzyme activity." (PMID 21234284, 2010). "However, this raises one of a number of pressing questions for the future, namely, how does NFκB activate basal glutaminase activity in transformed/cancer cells?" (PMID 21234284, 2010).
cancer (continued). "After identifying a common dependency of cisplatin‐resistant cancer cells upon extracellular glutamine, we then evaluate the utility of the long‐standing anti‐leukemic therapy asparaginase (ASNase)—which possesses both asparaginase and glutaminase activity—as a potential approach." (PMID 40784667, 2025). "To date, cancer cell glutamine addiction is still widely and naturally thought to involve the glutaminase I pathway, by which glutamine is first converted to glutamate via a GLS-catalyzed reaction and before being converted into α-KG through GDH or transaminases (GOT/GPT/PSAT)." (PMID 36959802, 2023). "Thus, the use of glutaminase inhibitors such as CB-839 could be a useful therapeutic strategy in cancer cells with high NQO1 expression since they can reduce glutamate availability, creating a metabolic bottleneck." (PMID 37175546, 2023). "The Complex I inhibitor IACS-010759 and the glutaminase inhibitor CB-839 both showed strong anti-tumor activities across cell lines and PDX models with SMARCA4/2-loss, suggesting that these clinical agents can be effective in treating SMARCA4/2-deficicent cancers." (PMID 37210563, 2023). "Besides, lower glutamine levels were detected in HCT than ANT accompanied by the increase of the glutamate/glutamine ratio and the glutaminase 1 (GLS1) gene expression level, probably owing to a high metabolic dependency on glutamine for the cancer cell survival and proliferation." (PMID 35406630, 2022). "Thus, reducing glutamate levels with glutaminase inhibitors or blocking extracellular cysteine absorption might similarly boost ROS levels in cancer cells to promote cell death." (PMID 36358687, 2022). "Indeed, the paradigm of focusing on cancer metabolism was freshly required beyond the dramatic flexibleness of tumor metabolic cascades reported in cancer cells challenged with multiplex inhibitors, including glycolysis and glutaminase inhibitors." (PMID 35912242, 2022). "Moreover, both glutaminase and glutamate dehydrogenase are overexpressed in many cancers." (PMID 35208185, 2022). "An example of metabolic inhibitors affecting non-immune cells of TME regards GLS inhibitors, which have been associated with synergistic anti-tumorigenic effects, since apart from suppressing cancer cell survival, reduced proangiogenic signals deriving from connective tissue." (PMID 34771610, 2021). "Therefore, inhibition of glutaminase-1 (GLS1), the first step in glutaminolysis, in cancers displaying glutamine dependency may lead to aspartate deprivation." (PMID 34827664, 2021). "In addition, cancer cells express more GLS1 (kidney-type glutaminase) and GDH than stromal cells." (PMID 34503536, 2021). "Thus, GLS has become a potentially ideal therapeutic target in cancer." (PMID 33513833, 2021). "However, certain cancer types (e.g., pancreatic, lung) demonstrate contradicting sensitivity to GLS inhibition in vitro and in vivo, suggesting that tumors may be more glutaminolysis independent in vivo than modeled in culture." (PMID 33669382, 2021). "However, the low levels of extracellular Gln to which cancer cells are exposed in vivo may maintain GLS expression at a low standard, thereby limiting the sensitivity of cells to its inhibitor." (PMID 35223460, 2021). "As discussed in the preceding section, SLC7A11high cancer cells are dependent on glutamine for glutamate-derived anaplerosis, which prompted the hypothesis that SLC7A11high cancer cells or tumors may be particularly sensitive to glutaminase inhibition." (PMID 33000412, 2021). "The role of GLS in cancer development appears to be highly context dependent and remains unclear." (PMID 32184390, 2020).
cancer (continued). "In addition, further studies are warranted to clarify the role of GLS-1 in these cancer cells." (PMID 32150977, 2020). "Other GLS inhibitors were also tested after manipulation of IDH1 R132H, Compound 2 or CB-839 inhibits proliferation preferentially in IDH mutated cells, but it has a poor BBB penetration, and compound 968 was able to sensitize cancer cells to mTOR-targeted therapies in mouse xenograft models." (PMID 32993063, 2020). "Besides GLS1, GLS2 is also related to reprogrammed glutaminase activity in cancer." (PMID 32174794, 2020). "Although previous studies have reported a very active GLS in cancer cells, a post-transcriptional regulation mediated by miRNAs could play an important role, so more studies are necessary in this field, to better understand the role of glutamine and glutamate metabolism in BC." (PMID 31100982, 2019). "Moreover, the expression of combined GLS- and GLS2-centered- signature-gene set regulated clinical prognosis in certain cancers which further predict that the functional partners of GLS and GLS2 contribute to significant CNAs and mutations and subsequently regulate the clinical outcomes in cancers." (PMID 30871151, 2019). "According to these findings, the absence of GS, associated to high GLS activity, makes cancer cells addicted for glutamine and might associate with a more invasive, aggressive and resistant phenotype." (PMID 29463059, 2018). "GLS messenger RNA (mRNA) expression, which could be indicator of cancer glutamine addiction, is higher in myeloma and other tumor types, such colon, liver, stomach, and thyroid compared to the surrounding healthy tissue and its blockade is known to hamper in some cases tumor progression." (PMID 29463059, 2018). "The anti-proliferative effect of metformin on cancer cells could be suppressed via increased glutamine metabolism, and combined treatment with glutaminase inhibitor and metformin might specifically enhance the beneficial effects of metformin in cancer treatment." (PMID 29323154, 2018). "However, it may be possible to use enzymes such as glutaminase and L-asparaginase to remove glutamine in vivo to impact cancer stem cells." (PMID 28245869, 2017). "Like any other chemotherapeutics, cancer cells may have resistance to glutaminase inhibitors." (PMID 28750681, 2017). "Kidney-type glutaminase (KGA) and glutaminase C (GAC) were encoded by GLS1 and liver-type glutaminase (LGA) was encoded by GLS2 GLS1 was broadly expressed in normal tissue and over-expressed in many cancer cells, thus played an important role in tumor metabolism." (PMID 29371926, 2017). "Additionally, NF-κB may exert a control on the expression of glutaminase in cancer cells through the regulation of miRNAs." (PMID 28598356, 2017). "However, there are arguments that L-asparaginase together with glutaminase inhibitor may exert a complete inhibition of glutamine metabolism and so enhancing the anti-tumor effect in cancer cells." (PMID 28750681, 2017). "Also, understanding the function of KGA and GAC in both physiological and pathological systems as it relates to neurodegeneration can be used for drug development that target glutaminase 1 enzyme for therapeutic purposes in cancer and neuroscience." (PMID 28439409, 2017). "The c-Myc is essential for driving enhanced glutaminolysis in cancer cells and thus maintains the mitochondrial function and oxidative phospshorylation as well as directly or indirectly (via miRNAs) regulates the glutamine transporters and mitochondrial glutaminase, GLS1." (PMID 25271736, 2014). "Cancer cells tend to exhibit the Warburg effect, in which cellular metabolisms proceed via: 1) an altered glucose metabolism characterized by a high rate of glycolysis followed by lactic acid fermentation; and 2) up-regulated glutaminolysis by increasing glutaminase activity." (PMID 25026281, 2014).
cancer (continued). "Therefore, targeting glutaminase as well as other enzymes responsible for the metabolic re-programming of cancer cells could offer some exciting and highly specific strategies for intervention against malignancies manifesting glutamine addiction." (PMID 21234284, 2010). "Our results demonstrated that these adaptations render cancer cells that survive CDK4/6 inhibition highly sensitive to MYC, glutaminase (GLS1), or mTOR inhibitors and hypoxic conditions." (PMID 40696167, 2025). "Despite the classic Warburg effect, amino acid metabolism, particularly glutamine catabolism via glutaminase and glutamate dehydrogenase, fuels the TCA cycle to meet the bioenergetic and biosynthetic demands of cancer cells." (PMID 40963133, 2025). "Gln hydrolysis can be catalyzed by two GLS isoforms due to differential RNA splicing, GLS1 (kidney-type glutaminase) and GLS2 (liver-type glutaminase), and both are expressed differentially across cancer types." (PMID 41439982, 2025). "Clinical trials are already underway investigating the efficacy of PD-1/PD-L1 inhibitors in combination with agents that disrupt cancer metabolism, such as ROS inducers, OXPHOS inhibitors, and glutaminase inhibitors." (PMID 39997327, 2025). "Consistent with prior studies investigating metabolic reprogramming in cancer, we observed significant upregulation of key cuproptosis-related genes, including FDX1, GLS, and CDKN2A, in tumor tissues compared to normal counterparts." (PMID 40410601, 2025). "The role of glutaminolysis, catalysed by glutaminase (GLS1), in cancer cells remains incompletely elucidated." (PMID 40259435, 2025). "Glutaminolysis is the process of glutamine breakdown catalyzed by glutaminase (GLS) and this process is required to produce energy in various types of cancer." (PMID 41303787, 2025). "Thus, inhibition of GLS may lead to the growth restriction of cancer cells." (PMID 40696413, 2025). "Once inside the cell, glutamine is converted to glutamate in the mitochondria by glutaminase 1 (GLS1) or GLS2—the first reaction in glutaminolysis, a process that is upregulated in cancer cells." (PMID 40552664, 2025). "In the realm of cancer therapeutics targeting metabolism, CB-839, a small molecule inhibitor specifically designed to target glutaminase (GLS), strategically manipulate the reliance of cancer cells on glutamine, is noteworthy." (PMID 39403716, 2024). "Glutaminase (GLS) is a crucial enzyme in the process of glutamine metabolism and has been found to play a role in several forms of cancer." (PMID 39408933, 2024). "Combined with 19 genes related to cuproptosis in the current cancer database, NFE2L2, PDHA1, PDHB, DLD, and GLS showed significant differences between the two groups." (PMID 38200445, 2024). "The glutaminase enzymes GAC and GLS2 catalyze the hydrolysis of glutamine to glutamate, satisfying the ‘glutamine addiction’ of cancer cells." (PMID 38438397, 2024). "GLS is the rate-limiting enzyme for glutaminolysis, and its inhibitor BPTES exhibited remarkable tumor-killing effects in cancers." (PMID 38386265, 2024). "The involvement of this SLC1A5-glutamine axis also supports the development of therapeutic interventions against this preferentially upregulated pathway in cancer and in this regard SLC1A5 and glutaminase inhibitors are already in experimental development." (PMID 39431017, 2024). "Oncogenic transcription factors like c-MYC and RAS can upregulate glutamine transporters and enzymes, such as alanine-serine cysteine transporter 2 (ASCT2) and glutaminase (GLS)-1, in cancer cells, increasing their metabolic activity." (PMID 39791706, 2024). "Glutaminase (GLS) is directly related to cell growth and tumor progression, making it a target for cancer treatment." (PMID 38965208, 2024).
cancer (continued). "There are two types of GA isozymes, named GLS and GLS2, which differ considerably in their expression patterns and can even perform opposing roles in cancer." (PMID 38929183, 2024). "Glutamate was also found to be regulated via glutaminase together with ALDH, contributing to cancer stemness." (PMID 39767805, 2024). "Glutaminase (GLS) is amenable for glutaminolysis, which is a process harnessed by cancer cells to feed their accelerated growth and proliferation in many malignant tumors." (PMID 36831355, 2023). "Glutaminase is a key target for glutamine metabolism, and GLS inhibitors have been used in various cancers." (PMID 37924140, 2023). "The kidney isoform of GLS (GLS1) is regulated by the oncogene MYC and we have shown that its activity and downstream Krebs cycle-independent pathways is crucial to cancer cell survival and proliferation." (PMID 37512481, 2023). "In contrast, eight regulators (PDHA1, ATP7A, LIPT1, LIPT2, GLS, ATP7B, GCSH, and CDKN2A) were upregulated in cancer tissues." (PMID 36672336, 2023). "In addition to available candidate drugs targeting Complex I and glutaminase, we develop the concept and provide proof of principle data supporting the potential clinical utility of alanine dietary supplementation for patients affected by these hard-to-treat cancers." (PMID 37210563, 2023). "Twenty years ago, Turner and McGivan documented, for the first time, co-expression of the GLS and GLS2 genes in a single cancer cell type." (PMID 38067269, 2023). "Mammalian cells express two GLS isoforms, namely kidney-type glutaminase (KGA or GLS1) and liver-type glutaminase (LGA or GLS2) that are dysregulated in a cancer type-specific manner." (PMID 36768660, 2023). "A total of 6 CRSGs were screened out, including CDKN2A, GLS, FDX1, PDHA1, PDHB, and DLD; most of them have been reported in the direct regulation of cuproptosis and cancer progression." (PMID 37287976, 2023). "Glutaminase catalyzes the production of glutamate from glutamine and supplies the former into the TCA cycle to support the proliferation of cancer cells, and glutamate is further metabolized to the antioxidant peptide glutathione." (PMID 37887398, 2023). "In the differential expression analysis of oral squamous cell carcinoma and adjacent tissues, LIAS and PDHB were inhibited in cancer tissues, while GLS and CDKN2A were promoted in cancer tissues." (PMID 36600313, 2023). "The authors showed that an increase in phosphoribosyl pyrophosphate amidotransferase (PPAT) and PPAT/GLS ratio is required to trigger nitrogen shift towards nucleotide biosynthesis in lung cancer and could be considered as a universal phenomenon in other cancer types apart from colorectal cancer." (PMID 35158820, 2022). "Here, we will focus on glutaminase C (GAC or GLS C), a shorter isoform of the kidney type GA (KGA or GLS) that is localized to mitochondria and frequently induced in cancer cells." (PMID 35008407, 2022). "The proposed theme is that when glutamine is taken up by cancer cells via SLC1A5, it is converted into glutamate by GLS." (PMID 36499623, 2022). "GLS (Glutaminase), which is also known as the “kidney-type” glutaminase (GLS1), is a metabolism enzyme that plays a critical role in glutaminolysis that promotes cancer cell proliferation, including HCC." (PMID 36177029, 2022). "Alternatively, the corresponding transporters and enzymes have been found to be highly expressed in these cancer patient samples, such as SLC1A5, GLS, and GLUD1." (PMID 36077501, 2022). "The differential expression analyses of OSCC tissues and para-cancer tissues demonstrated that LIAS and PDHB were suppressed in cancer tissues, but GLS and CDKN2A were accelerated." (PMID 35875097, 2022).